SLC22A23 (solute carrier family 22 member 23)
Synonyms: C6orf85; FLJ22174
Tractability: Antibody: UniProt predicts a signal peptide or a membrane-spanning region; its Gene Ontology location is reachable by antibodies, with medium confidence. PROTAC: ubiquitination databases record sites on it; its protein half-life has been measured.
Gene: Protein-coding gene on chromosome 6 (3,268,962 to 3,457,050, reverse strand). Ensembl gene ENSG00000137266.
Subcellular location: Membrane
Subcellular location (Human Protein Atlas): Nucleoplasm; Vesicles; Cytosol
Gene Ontology:
Molecular function: protein binding; transmembrane transporter activity
Biological process: transmembrane transport
Cellular component: membrane; plasma membrane
Genetic constraint (gnomAD): Loss-of-function variants: 25 observed, 55.45 expected, observed/expected ratio (o/e) 0.45, 90% interval 0.33 to 0.63. The upper end of that interval is the gene's LOEUF score, 0.63, which puts it in group 2 of 6, group 1 being the genes least tolerant of losing a copy. Missense variants: 793 observed, 912.06 expected, observed/expected ratio (o/e) 0.87, 90% interval 0.82 to 0.92. Synonymous variants: 428 observed, 410.1 expected, observed/expected ratio (o/e) 1.04, 90% interval 0.96 to 1.13.
Homologues: Orthologues: chimpanzee SLC22A23 (99% identical), rat Slc22a23 (92% identical), mouse Slc22a23 (92% identical), dog SLC22A23 (89% identical), pig SLC22A23 (88% identical), macaque SLC22A23 (84% identical), rabbit SLC22A23 (81% identical), guinea pig SLC22A23 (80% identical), tropical clawed frog slc22a23 (67% identical), zebrafish slc22a23 (54% identical), Caenorhabditis elegans K05F1.6 (18% identical), Caenorhabditis elegans oct-2 (18% identical), and 38 more. Paralogues in human: SLC22A17 (26% identical), SLC22A31 (22% identical), SLC22A7 (19% identical), SLC22A3 (19% identical), SLC22A2 (18% identical), SLC22A5 (18% identical), SLC22A8 (18% identical), SLC22A14 (18% identical), SLC22A4 (18% identical), SLC22A1 (18% identical), SLC22A6 (17% identical), SLC22A10 (17% identical), and 10 more.
Diseases named in the same sentence as SLC22A23 in open-access papers:
SLC22A23 is named in the same sentence as 20 diseases in open-access papers, as found by Europe PMC text mining. Sharing a sentence is not in itself a finding about the gene and the disease. The quoted sentences say what the papers report.
endometriosis (3 papers, 2018 to 2024). The growth of functional endometrial tissue in anatomic sites outside the uterine body. "The single nucleotide polymorphism (SNP) associated with endometriosis patients is located in the 3’-untranslated region of the Slc22a23 gene, which is a predicted target site for microRNA binding and may participate in downregulation of Slc22a23 gene expression." (PMID 39197039, 2024). "Some other polymorphisms of the SLC22A23 gene have also been associated with complex diseases that have an inflammatory component such as IBD, endometriosis-related infertility which is an indicator of the transporter activity of the SLC22A23 gene." (PMID 29703252, 2018). "Although the exact function is unknown, single nucleotide polymorphisms (SNPs) which are located in SLC22A23 gene were associated with inflammatory bowel disease (IBD), endometriosis-related infertility and the clearance of antipsychotic drugs." (PMID 29703252, 2018). "SLC22A23 has no confirmed substrates, but SNPs and mutations within this gene have medically relevant phenotypic associations such as QT elongation, inflammatory bowel disease, endometriosis-related infertility, and the clearance of antipsychotic drugs." (PMID 32150922, 2020).
laryngeal squamous cell carcinoma (3 papers, 2018 to 2024). A squamous cell carcinoma that arises from the larynx. "DNA demethylation occurs at the Slc22a23 gene locus in endometrial stromal cells, and the Slc22a23 gene transcript is increased in the endometrial stromal cells and laryngeal squamous cell carcinoma." (PMID 39197039, 2024).
laryngeal carcinoma (2 papers, 2018 to 2021). Carcinoma that arises from the laryngeal epithelium. "Our results indicate that SLC22A23 may play a role in the development of laryngeal cancer." (PMID 29703252, 2018).
asthma (1 paper, 2019). "For example, SLC22A23 is not only a locus for Crohn’s disease but also a risk gene for bronchodilator responsiveness in asthma." (PMID 30239845, 2019). "Moreover, it has been demonstrated that SLC22A23 and SLC25A15 are strongly associated with the bronchodilator responsiveness of asthma." (PMID 30239845, 2019).
larynx cancer (1 paper, 2018). A primary or metastatic malignant neoplasm involving the larynx. "In conclusion, as a preliminary report our results indicate that SLC22A23 acts as one of the membrane transporters in larynx cancer which warrants further investigation in larynx cancer." (PMID 29703252, 2018). "Statistically, significant upregulation of the SLC22A23 mRNA was observed in laryngeal tumor tissues (p = 0.001)." (PMID 29703252, 2018). "To understand the role of the SLC22A23 gene in laryngeal carcinogenesis, we investigated its mRNA expression level in laryngeal tumor tissue and adjacent non-cancerous tissue samples obtained from 83 patients by quantitative real-time PCR." (PMID 29703252, 2018).
Obesity (1 paper, 2020). Accumulation of substantial excess body fat. "Based on the obtained results, the ZSCAN32, PLCD4, HOXC13, and ADCY9 from obesity predicted genes, as well as LIMA1, and SLC22A23 from CRC predicted genes were significantly related to CRC survival rate." (PMID 33073494, 2020).
triple-negative breast carcinoma (1 paper, 2018). An invasive breast carcinoma which is negative for expression of estrogen receptor (ER), progesterone receptor (PR), and human epidermal growth factor receptor 2 (HER2). "On the other hand SLC22A23 is identified as a prognostic gene to predict the recurrence of triple-negative breast cancer." (PMID 29703252, 2018).
cancer (1 paper, 2018). A tumor composed of atypical neoplastic, often pleomorphic cells that invade other tissues. "So far there is no study in the literature investigating the expression rate of the SLC22A23 gene in cancer." (PMID 29703252, 2018).
larynx (1 paper, 2018). "Therefore, in view of our DEGs results we investigated expression levels of the SLC22A23 gene in larynx tumor samples and observed up-regulation of the SLC22A23 mRNA levels in a significant proportion of the tumors." (PMID 29703252, 2018).
psychiatric disorder (1 paper, 2024). A disorder characterized by behavioral and/or psychological abnormalities, often accompanied by physical symptoms. "The Slc22a23 knockout rats generated in this study could be a useful animal model to elucidate the pathogenic mechanisms of lifestyle-related NCDs and psychiatric disorders prevalent in our modern nutrient-rich environment." (PMID 39197039, 2024). "Overexpression of the Slc22a23 gene in a nutrient-rich environment may be involved in the development of lifestyle-related NCDs and psychiatric disorders observed in the DOHaD phenotype." (PMID 39197039, 2024).
tumor (1 paper, 2018). "We observed increased SLC22A23 mRNA expression in 46 of 83 tumor tissues (55.4%) and decreased expression in 30 tissues (36.1%) when compared to their normal counterparts." (PMID 29703252, 2018). "We found that SLC22A23 expression was increased in 46 of 83 tumor tissues (55.4%) and was decreased in 30 of 83 (36.1%) tumor tissues compared to normal tissues." (PMID 29703252, 2018). "We examined the altered expression level of the SLC22A23 gene using Real-Time PCR in 83 tumor samples and adjacent non-cancerous tissue samples." (PMID 29703252, 2018).
SLC22A23 also shares sentences with these, for which no sentence is quoted: inflammatory bowel disease (3 papers); Infertility (2); Anxiety (1); cholangiocarcinoma (1); Crohn disease (1); glioblastoma (1); glioma (1); hay fever (1); inflammation (1).